NQO1 (NAD(P)H quinone dehydrogenase 1)
Diseases named in the same sentence as NQO1 in open-access papers (continued):
Sharing a sentence is not in itself a finding about the gene and the disease.
breast carcinoma (continued). "Here, the authors show, in breast cancer models, that inflammatory mediators can potentiate complex I inhibitor phenformin cytotoxicity through STAT1-mediated downregulation of the reactive oxygen species scavenger NQO1." (PMID 34083537, 2021). "On the other hand, treatment with R-SFN increased the expression of the NQO1 gene both in breast cancer (MCF7 and MDA-MB-231) and non-tumorigenic breast cells." (PMID 33064289, 2021). "Here, the use of siRNA against CUL3 in MCF-7 breast cancer cells increased the levels of NRF2-regulated proteins, including GCL, NQO1, AKR1C1, UGDH, TXN and the drug transporter ABCC1, ultimately conferring a resistance to the oxidants and conventional anticancer agents." (PMID 33805996, 2021). "Previous reports suggest that β-lap is a competent tumor-selective agent against many NQO1+ solid cancers, such as NSCLC, pancreatic and breast cancers, while the antitumor effect of this drug in liver cancer is still unknown." (PMID 34676172, 2021). "Breast cancer cells expressing NQO1 shRNAs are not further sensitized to IFNγ and phenformin co-treatment, suggesting that NQO1 is an essential target gene that confers the antitumorigenic effects of phenformin." (PMID 34083537, 2021). "It has also been reported that a combination of PARP inhibitors and β-lapachone, a natural quinone, exhibits synergistic anti-tumor activity against NAD(P)H:quinone oxidoreductase 1 (NQO1)-overexpressing cancers, such as non-small-cell lung cancer, pancreatic cancer, and breast cancer." (PMID 30631755, 2018). "Previous studies found a correlation between a high level of NQO1 and LN metastasis in breast cancer and NSCLCs, which was not seen in this study." (PMID 28501854, 2017). "We observed that the positive rate of NQO1 expression was markedly higher in the breast cancer tissues than that in the adjacent non-tumour tissues." (PMID 28578385, 2017). "NQO1 mRNA levels were examined in eight pairs of breast cancers and adjacent non-tumor breast tissues using qRT-PCR." (PMID 24499631, 2014). "Western blot data also demonstrated that NQO1 protein was highly expressed in breast cancer tissues compared with adjacent non-tumor tissues." (PMID 24499631, 2014). "Compared with adjacent non-tumor tissues, NQO1 protein was found to be significantly up-regulated in breast cancer using IHC." (PMID 24499631, 2014). "The results revealed that NQO1 protein is frequently upregulated in breast cancers compared with hyperplasia and adjacent non-tumor breast tissues." (PMID 24499631, 2014). "A total of 176 breast cancer patients with strict follow-up, 45 ductal carcinoma in situ (DCIS), 22 hyperplasia and 52 adjacent non-tumor breast tissues were selected for immunohistochemical staining of NQO1 protein." (PMID 24499631, 2014). "Western blot and qRT-PCR results also demonstrated that the mRNA and protein levels of NQO1 in four cases of fresh breast cancer samples were elevated compared with the adjacent non-tumor tissues." (PMID 24499631, 2014). "Moreover, it has been demonstrated that NRF2 induces the expression of TRX1 in non-small cell lung cancer and NADPH quinone oxidoreductase 1 (NQO1) in human colorectal and breast cancer cell lines, which have been shown to increase HIF-1α levels by prolonging its lifespan (stabilization)." (PMID 40426975, 2025). "Glycolysis blockade with 2- DG or 3-BrPA reversed NAD(P)H:quinone oxidoreductase-1 (NQO1)-induced EMT by inhibiting vimentin, Snail, Slug and Twist, and up-regulating E-cadherin, leading to attenuated NQO1-induced glycolysis and metastasis in breast cancer cells." (PMID 32839493, 2020).
breast carcinoma (continued). "Thus, we speculate that pharmacological inhibition of NQO1 and GCLC may be new therapeutic strategies for overcoming tamoxifen-resistance in breast cancer patients." (PMID 28411284, 2017). "Thus, pharmacological inhibition of NQO1 and GCLC may be new therapeutic strategies for overcoming tamoxifen-resistance in breast cancer patients." (PMID 28411284, 2017). "Additionally, NQO1 was overexpressed in breast cancer patients with metastasis compared with patients without metastasis." (PMID 28578385, 2017). "In addition, the breast cancer cell death was substantially higher although the expression of FN3K enhanced with certain kinase inhibitors used for breast cancer treatment and the Nrf2 signalling was modulated consequently NQO1 and HO-1 antioxidant protein expression patterns also declined." (PMID 37910519, 2023). "Thus, NQO1 and GCLC may be i) new prognostic biomarkers, ii) novel therapeutic targets and iii) companion diagnostics, for predicting and overcoming tamoxifen-resistance in different subsets of ER(+) breast cancer patients." (PMID 28411284, 2017). "For example, our previous study demonstrated that NQO1 protein expression was significantly elevated in breast cancer tissues compared with hyperplasia or adjacent non-tumor tissues, indicating that NQO1 up-regulation may occur in the initiation stage of breast cancer progression." (PMID 25880877, 2015). "We evaluate the effect of FRV–1, FRV–2, and methyl-analogs on the viability of breast fibroblast RMF-621 and two breast cancer cell lines: MCF7 (naphthoquinone oxidoreductase 1, NQO1 positive) and MDA-MB-231 (NQO1 negative)." (PMID 37627592, 2023). "Further evidence of imbalance in estrogen homeostasis derives from the greater expression of estrogen-protective enzymes, COMT and NQO1, in women without breast cancer and greater expression of estrogen-activating enzymes, CYP19 and CYP1B1, in breast tissue of women with breast cancer." (PMID 26979321, 2016).
hepatoma (81 papers, 2010 to 2026). "The high expression of NQO1 is associated with tumor size and degree of venous infiltration of hepatocellular carcinoma, making it a potential biomarker for prognostic evaluation of hepatocellular carcinoma patients." (PMID 37405532, 2024). "In hepatocellular carcinoma cells, Nrf2 expression contributed to ferroptosis resistance, in association with its downstream effector proteins, such as HO-1, NQO-1, and ferritin." (PMID 30583467, 2018). "Similar observations were recently made in a mouse model of hepatocellular carcinoma where chronic stress (Diethylnitrosamine treatment) led to reduced expression of Nrf2 target genes including Gst and Nqo1 mRNA in p62-deficient livers." (PMID 27526095, 2016). "The STCs were tested for their nuclear factor erythroid 2-related factor 2 (NRF2) activation ability in murine hepatoma cells (Hepa1c1c-7) by determining their NAD(P)H quinone oxidoreductase 1 (NQO1) inducing ability and expression of NRF2-associated antioxidant genes." (PMID 36830033, 2023). "However, when we divided the subgroups, we noticed significantly decreased associations were found among renal cell carcinoma, hepatocellular carcinoma, gastric cancer and NQO1 rs1800566 polymorphism." (PMID 36338728, 2022). "Similarly, studies in cancer showed that rs1800566 polymorphism of NQO1 was an important risk factor for hepatocellular carcinoma." (PMID 36338728, 2022). "More importantly, the NQO1 Pro187Ser polymorphism has been shown associated with increased risk for many different types of cancers, including colorectal cancer, lung cancer, esophageal cancer, and hepatocellular carcinoma." (PMID 24884893, 2014). "The present comprehensive meta-analysis suggested the NQO1 rs1800566 polymorphism was an important genetic factor in the risk of cancer, especially in Caucasians, moreover, decreased associations in gastric cancer, hepatocellular carcinoma and renal cell carcinoma were proved." (PMID 36338728, 2022). "Preliminary experiments confirmed that S. multicaulis acts as an inducer of chemopreventive NAD(P)H: Quinone oxidoreductase 1 (NQO1) protein expression in a murine hepatoma (Hepa1c1c7) chemoprevention model." (PMID 42265167, 2026). "It should also be noted that the basal level of NQO1 in HepG2 and other hepatocellular carcinoma cells is relatively high." (PMID 40063860, 2025). "The treatment of murine hepatoma (Hepa-1c1c7) cells with swietenine also induces NAD(P)H quinone oxidoreductase 1 (NQO1) dose-dependently, supporting the activation of NRF2 observed in RAW264.7 cells." (PMID 35624777, 2022). "To determine the inducer potency of PRL-295, we used a quantitative bioassay in murine hepatoma (Hepa1c1c7) cells, which measures the enzyme activity of the classical Nrf2 target, NAD(P)H:quinone oxidoreductase 1 (NQO1) as the readout." (PMID 35036882, 2022). "In THLE-2, immortalized normal hepatocytes treated with these conjugates resulted in the activation of Nrf2 and increased expression in SOD-1 and NQO1, while the opposite effect was observed in the HepG2 hepatoma cells." (PMID 34358114, 2021). "Studies have shown that overexpressed NQO1 can enhance the apoptosis escape and play an important role in maintaining the proliferation of hepatocellular carcinoma cells." (PMID 33424998, 2020). "For example, (+)-tephropurpurin, a chalcone isolated from Tephrosia purpurea induced NQO1 activity in the murine hepatoma hepa-1c1c7 model." (PMID 29788962, 2018). "In murine hepatoma cells, both SFN and SFN-NAC caused dose-related cell growth inhibition and NAD(P)H quinone dehydrogenase 1 (NQO1) induction." (PMID 29747418, 2018). "In hepatocellular carcinoma, HepG2 and Hepa1-6 cells, genetic knockdown of Nrf2, HO-1, quinone oxidoreductase 1 (NQO-1), or ferritin also promoted erastin- and sorafenib-induced ferroptosis." (PMID 30583467, 2018).
hepatoma (continued). "After 48 h of exposure, 2,3-dehydrosilydianin at concentrations of 25 μM and higher significantly elevated the activity of NQO1 in murine hepatoma Hepa1c1c7 cells." (PMID 28450126, 2017). "NQO1 promotes hepatocellular carcinoma invasion and metastasis through enhancement of ERK-NRF2." (PMID 40649911, 2025). "In another report, SIRT6 has been shown to mediate the tumor-promoting effect of NAD(P)H:quinone oxidoreductase 1 (NQO1) on hepatocellular carcinoma through the activation of AKT serine/threonine kinases in PLC/PRF/5 and Huh7 cell lines and an orthotopic tumor cell implantation mouse model." (PMID 36831330, 2023). "drew a conclusion that NQO1 could promote an aggressive phenotype in hepatocellular carcinoma via enhancing ERK-NRF2 signaling." (PMID 37182175, 2023). "Furthermore, HBV X protein (HBx) induces epigenetic silencing of NAD(P)H:quinone oxidoreductase 1 (NQO1) in hepatoma cells through promoter hypermethylation." (PMID 35664791, 2022). "Furthermore, in hepatocellular carcinoma cells, knockdown of p62, NQO1, FTH1 and HMOX1 promoted ferroptosis in response to erastin and sorafenib." (PMID 34836129, 2021). "Additionally, the overexpression of NQO1 inhibits hepatocellular carcinoma cell proliferation through AMPK/PGC-1α pathway." (PMID 31886179, 2019). "Furthermore, 7-O-galloylquercetin was found to increase the protein levels of Nrf2 and HO-1, and also the activity of NQO1 in murine hepatoma Hepa1c1c7 cells." (PMID 27777014, 2016). "It is noteworthy that in nutrigenomic studies comparing potency of phytochemicals, SFN exhibits the highest potency determined by its “CD value”, defined as the concentration of a compound required to double NQO1 specific activity in Hepa 1c1c7 murine hepatoma cells." (PMID 27625902, 2015). "Lycopene metabolite, apo-8’-lycopenal that can be found in rat liver and human plasma after consuming lycopene-containing food, induced nuclear translocation, Nrf2-ARE binding activity, HO-1 and NQO1 genes and proteins expression in human hepatoma cell lines, HepG2." (PMID 24559113, 2014). "The enzyme activity of NQO1, one of the antioxidant and anticarcinogenic biomarker enzymes, was dose-dependently induced by AA extract in the range of 12.5 to 200 μg/mL in murine hepatoma hepa1c1c7 cells." (PMID 24988450, 2014). "A quantitative bioassay evaluating the induction of NAD(P)H:quinone oxidoreductase 1 (Nqo1), the prototypical Nrf2 target gene, in Hepa1c1c7 murine hepatoma cells was developed and still remains a major screening tool for potential activators of the Keap1-Nrf2 pathway." (PMID 23056183, 2012). "Moreover, in hepatocellular carcinoma, NQO1 overexpression decreases the Bcl-2 expression." (PMID 34481509, 2021). "In hepatoma cells, erastin induces NQO1 expression in an NFE2L2-dependent manner, and knocking down NQO1 enhances erastin-induced growth arrest." (PMID 39025451, 2024). "In hepatocellular carcinoma, the degradation of KEAP1 mediated by P62 assists the activation of NAD(P)H quinone dehydrogenase 1 (NQO1), heme oxygenase 1 (HO1), and ferritin heavy chain 1 (FTH1) down-stream of NRF2." (PMID 37152054, 2023). "For instance, TCDD induces NQO1 gene expression in human hepatoma cell lines, but antioxidant N-acetyl cysteine (NAC) or CYP1A1 siRNA decreases NQO1 gene induction, indicating that NQO1 induction is controlled by CYP1A1 activity through oxidative stress." (PMID 35204110, 2022). "Relatively high NQO1 and low catalase expression in various HCC patients and cell lines indicates a potent therapeutic window in liver carcinoma for β-lap, and our above data confirmed that β-lap efficiently represses tumor cell growth in vitro." (PMID 34676172, 2021). "Nrf2 regulates cellular iron and ROS metabolism via p62-Keap1-NRF2 pathway where it protects hepatocellular carcinoma cells against ferroptosis through upregulation of multiple genes (heme oxygenase-1 (HO1) and quinone oxidoreductase-1 (NQO1))." (PMID 34007410, 2021).
hepatoma (continued). "The enzyme NAD(P)H quinone oxidoreductase 1 (NQO1) inducer activity of the methanolic extract of D. anethifolia (80%), gained from the aerial parts, was assessed against murine hepatoma (Hepa1c1c7) cells." (PMID 32752066, 2020). "The increase in CD36 was confirmed in cultured human hepatoma cells, where either SIRT3 inhibition or knockdown in the presence of palmitate raised both CD36 and NQO1." (PMID 32912335, 2020). "The catalytic activity of NQO1 was increased upon SFN treatment in rats, neonatal rat cardiomyocytes, murine hepatoma Hepa1c1c7, and human prostate cancer LNCaP cells." (PMID 29144397, 2017). "For example, microcystin increases the Nrf2-target genes Nqo1 and Ho-1 in NIH3T3 cells and HepG2 cells, and addition of microcystin to hepatoma HepG2 and Hep3B cells results in microcystin uptake into hepatocytes and the release of Nrf2 into the nucleus." (PMID 24667526, 2014). "We also evaluated CYP1A1, CYP1A2, NQO1, and UGT1A1 expression following leflunomide exposure in HepG2 human hepatoma cells." (PMID 20957046, 2010). "Lack of NQO1 induced the highest level of nitric oxide (NO) and ROS in hepatocellular carcinoma, promoting apoptosis and autophagy of tumor cells." (PMID 40429916, 2025). "In fact, the knockdown of p65 by siRNA enhanced the NRF2-mediated activation of HO-1, GPX2, and NQO1 genes in hepatoma HepG2 cells, whereas co-transfection of HO-1(ARE), GPX2(ARE), or NQO1(ARE)-Luc reporters with either NF-κB, p65, or IKKβ expressing vectors inhibited ARE-driven expression." (PMID 38539832, 2024). "Consistent with our results, NQO1 promotes an aggressive phenotype in hepatocellular carcinoma by amplifying ERK-NRF2 signaling; immunohistochemical analysis showed that the protein levels of NRF2 and NQO1 were higher in carcinoma tissues than in benign follicular adenomas and hyperplastic nodules." (PMID 35805773, 2022). "It has been reported that activation of Nrf2 inhibited NAFLD and NASH through upregulating heme oxygenase-1 (HO-1) /NAD(P)H:quinone oxidoreductase 1 (NQO1)/glutathione S-transferase (GST), then promoted hepatocellular carcinoma by competing with Keap1 or through FGFR4–GSK3β signal pathway." (PMID 33114130, 2020). "As in mouse cells and tissues, treatment with TBE-31 or the naturally occurring Nrf2 activator sulforaphane (SFN) upregulated the expression of CES1 in the human hepatoma cell line HepG2, which has high basal levels of CES1, in a manner resembling that of NQO1 and GCLC." (PMID 33103077, 2020). "In the study, we found that therapy target genes of Jianpi Jiedu decoction were mainly involved in metabolism and apoptosis in hepatocellular carcinoma, and there was a close relationship between the prognosis of hepatocellular carcinoma and the genes of CCNB1, NQO1, NUF2, and CHEK1." (PMID 33424998, 2020). "The influence of betanins on the activation of Nrf2 and the expression of GSTA, GSTP, GSTM, GSTT, NQO1, and HO-1 was assessed in human non-tumor THLE-2 and hepatoma-derived HepG2 hepatic cell lines." (PMID 31018549, 2019).